TAGLN (transgelin)
Diseases named in the same sentence as TAGLN in open-access papers (continued):
Sharing a sentence is not in itself a finding about the gene and the disease.
tumor (continued). "For instance, TAGLN is a tumor suppressor that is downregulated in multiple cancers, and its loss seems to be an early event in cell transformation, coinciding with alterations in cellular plasticity." (PMID 30918060, 2019). "TAGLN is an actin-binding protein family that comprises three isoforms with theorized roles in smooth muscle differentiation, tumour development, lymphocyte activation, and brain chemistry." (PMID 29615809, 2018). "Consistent with our findings, several studies from other laboratories have also suggested a similar tumor-promoting function of transgelin." (PMID 29416680, 2018). "Recent studies have provided further evidence that transgelin is also both a tumor suppressor and a variable tumor biomarker, which depends on the tumor type, stage, and experimental model." (PMID 30423940, 2018). "Prior studies suggest that transgelin is capable of both activating and repressing genes involved in tumor progression, although only a small number of individual genes have been examined to date." (PMID 26847345, 2016). "In both instances, the member of the isogenic pair that had higher transgelin levels also had a greater tumor burden." (PMID 26847345, 2016). "Downregulation of these proteins and Transgelin, which was validated by IHC, suggests that pericyte recruitment defect, which leads to leaky microvessel walls and promotes tumor metastasis." (PMID 27270312, 2016). "Although the role of transgelin in cancer is controversial, a number of studies have shown that elevated levels correlate with aggressive tumor behavior, advanced stage, and poor prognosis." (PMID 26847345, 2016). "Increases or decreases in transgelin levels have reciprocal effects on tumor cell behavior, with higher expression promoting metastasis." (PMID 26847345, 2016). "Early studies showed that expression is down-regulated in early-stage cancer models, leading to the idea that transgelin is a tumor suppressor." (PMID 26847345, 2016). "Some researchers consider Transgelin to be a tumor suppressor, while others have reported it promotes cancer cell migration and invasion." (PMID 27270312, 2016). "The power of TAGLN promoter hypermethylation as an epigenetic diagnosis biomarker seems promising and should be validated for detection of tumor DNA from serum, plasma, or nipple and ductal fluids in a large, prospective screening study." (PMID 26421063, 2015). "While some studies suggest a TSG function for TAGLN due to downregulation in different types of tumors, others define tumor-promoting activities or overexpression in cancer." (PMID 26421063, 2015). "Since TAGLN was frequently hypermethylated and consistently downregulated in both the BC cell lines and three independent panels of tumor tissues, we analyzed the functional role of TAGLN in BC and NTB cells." (PMID 26421063, 2015). "In order to assess the contribution of CAFs-TAGLN to tumor metastasis in vivo, we emplyed a xenograft model." (PMID 23510049, 2013). "Using small interfering RNA (siRNA), we found that CAFs enhanced tumor metastasis through upregulated TAGLN in vitro and in vivo." (PMID 23510049, 2013). "Transgelin is also a specific protein of smooth muscle cells, but its involvement in tumoral processes as a novel tumor suppressor protein has been documented." (PMID 22506042, 2012). "This list includes PLA2G4A, HMGA2, TAGLN and TUSC3, all of which have been implicated in other neoplasias." (PMID 23046790, 2012). "Transgelin (SM22α) is a cytoplasmic actin-binding protein, expressed by mesenchymal cells and tumor fibroblasts and which represses TGF-β-induced MMP-9 expression, reduces cell migration, and has tumor suppressor properties." (PMID 21549007, 2011). "Future studies need to investigate the role of ANTXR1 expression in other pathways like EGFR, the complement and coagulation cascades, as well as metastatic pathways including the potential role of TEM8 in the EMT process (with uPA and transgelin), and its importance in tumor biology." (PMID 39917181, 2024).
tumor (continued). "Immunohistochemically, the tumor was positive for transgelin, desmin, and h-caldesmon." (PMID 37466765, 2024). "However, the latest researches hinted that transgelin exerts the important roles in tumor‐suppressive and oncogenic functions in the different types of cancers." (PMID 39676863, 2024). "While traditionally considered a marker of smooth muscle differentiation, recent studies have unveiled the involvement of TAGLN in cancer biology, particularly its upregulation in stromal cells within the tumor microenvironment and its correlation with poor prognosis in several cancers." (PMID 39308508, 2024). "This may occur due to the CAFs transgelin-induced secretion of pro-inflammatory cytokines, ultimately accelerating tumor progression." (PMID 36990991, 2023). "Previous studies have highlighted TAGLN as a tumor metastasis initiator." (PMID 36990991, 2023). "Hypermethylation of TAGLN promoter has been shown to decrease TAGLN expression in tumor cells." (PMID 34902367, 2022). "Also, pathologic grade (P = 0.002), tumor metastasis (P < 0.001), and enneking stage (P < 0.001) were significantly related to the TAGLN." (PMID 35665757, 2022). "TAGLN is a well-known marker of fibroblasts, and the immunohistochemistry (IHC) analysis of TAGLN also verified the increasing proportion of fibroblasts in tumor tissues relative to adjacent normal tissues." (PMID 36104333, 2022). "TAGLN could play an essential role in the biological processes of tumor cell proliferation, apoptosis, migration, invasion, and metastasis." (PMID 35665757, 2022). "As for fibroblasts, we used the deconvolution analysis to reveal the higher proportion of fibroblasts in tumor tissues compared to adjacent normal tissues, and we used the marker of fibroblast, TAGLN, to verify the higher proportion of fibroblasts in tumor tissues compared to normal tissues." (PMID 36104333, 2022). "Relevant study show that TAGLN may be closely related to the canceration or migration and diffusion of tumors and is abnormally expressed in many tumor diseases." (PMID 35665757, 2022). "In addition, TAGLN dysregulation has been observed in different types of tumors, suggesting a role in tumor proliferation and invasiveness." (PMID 34902367, 2022). "We speculate that Transgelin may play a tumor suppressive role in the invasion and metastasis of ESCC." (PMID 34552870, 2021). "Recent studies have also shown that Transgelin plays an important role in tumor evolution." (PMID 34552870, 2021). "In addition, some studies have found that Transgelin can also be used as signal molecules to participate in cell growth and extracellular matrix degradation and is expressed in various tumor tissues to varying degrees." (PMID 34552870, 2021). "Transgelin is necessary for the proliferation of ccRCC cells, which contributes to aggressive tumor behavior and may be potentially used as a marker of sunitinib non-responsiveness in mccRCC tumors." (PMID 34572331, 2021). "However, further studies on TAGLN revealed its strong potential as a tumor metastasis initiator 18-20." (PMID 32754278, 2020). "Finally, strong association between elevated expression of TAGLN and TGFβ1 gene expression in CRC tumor samples and poor prognosis further support the association between TAGLN and advanced CRC disease." (PMID 32393769, 2020). "The restoration of the TAGLN-induced inhibition of colon carcinogenesis in vivo and in vitro suggested that TAGLN might potentially function as a novel tumor suppressor." (PMID 31591355, 2019). "Finally, TAGLN, which was identified as an important downregulated factor with a potential tumor suppressor function, is significantly downregulated in almost all cancer types listed here." (PMID 30918060, 2019). "Besides, the results of RT-qPCR revealed that TAGLN expressions were higher in normal tissues than the paired tumor tissues." (PMID 31591355, 2019).
tumor (continued). "TAGLN and TAGLN2 primarily participate in processes associated with a remodeling of actin cytoskeleton and their role in differentiation has been mainly described in tumor cells." (PMID 31355153, 2019). "Several early studies reported that downregulation of transgelin was associated with a poor overall survival (OS) in CRC patients, suggesting that transgelin might act as a tumor suppressor." (PMID 29416680, 2018). "HOPX (4.26/4.11-fold) is a known colon stem cell marker and is associated with the suppression of tumor metastasis, and TAGLN (2.66/3.73-fold) was found as a novel tumor suppressor and its post-surgical high expression was reported to be associated with good prognosis in stage III CRCs." (PMID 28455965, 2017). "TAGLN is involved in many biological functions, including tumor suppression." (PMID 28248256, 2017). "R-Ras and Transgelin showed different expression patterns in the para-tumor tissues." (PMID 27270312, 2016). "However, in multivariate Cox-regression analyses, only R-Ras and AJCC stage were prognostic factors for OS, while only Transgelin and tumor differentiation were prognostic factors for DFS." (PMID 27270312, 2016). "Indeed, the results of our ROC analyses with high sensitivity and specificity values, point out TAGLN gene methylation as a good candidate for a tumor marker, with 83.14 % sensitivity and 100 % specificity." (PMID 26421063, 2015). "Accordingly, extensive staining of TAGLN in the tumor stroma was also found in our panel of breast tissues stained by IHC, while TAGLN gene expression was specifically downregulated in tumor tissues of all grades and pathological types, when compared to normal tissues." (PMID 26421063, 2015). "Transgelin is also a tumor suppressor in several types of cancers." (PMID 25577646, 2015). "Moreover, 10-year relapse-free survival (RFS) of patients was significantly decreased with higher tumor methylation of the TAGLN probes compared to the patients with lower levels of methylation (P = 0.0059)." (PMID 26421063, 2015). "Most previous studies reported that transgelin acted as a tumor suppressor." (PMID 25109740, 2014). "Next, to investigate whether the transgelin expression level was altered in accordance with tumor progression, we compared the transgelin levels in the two tumor tissues resected at different times from the same patient." (PMID 25109740, 2014). "CAFs with increased TAGLN expression levels may enhance tumor cell invasion and migration ability which promote an enhanced expression of MMP-2." (PMID 23510049, 2013). "Differential expression analysis of the metastatic and primary tumor samples shows that a large number of the most highly downregulated genes such as TAGLN, ACTG2, TPM1, MYH111 and DES have been previously identified as expressed mostly in the prostatic stromal cells." (PMID 17430594, 2007). "Collectively, these results suggest that PZP-epithelial cell interaction in the breast could impact the levels of select chemokines/cytokines in the breast environment (IL-6 and TAGLN, for example) with consequential effects on the normal and/or tumor immune environment." (PMID 37709737, 2023). "Repression of transgelin may therefore mediate tumor suppressive effects of miR-34a in CRC." (PMID 36147476, 2022). "Indeed, THBS2 and TAGLN expression was higher in the samples with low tumor cellularity, inferring at least some expression may be due to the higher stromal content of the samples." (PMID 36222710, 2022). "The most prominent actions of TAGLN may favor tumor cell motility and invasion." (PMID 23510049, 2013). "Thus, TAGLN may enhance tumor metastasis through the MMP-2 enzymes degrade the basement membranes (eg. collagen IV)." (PMID 23510049, 2013). "This contrasts with healthy skin where APOD+ fibroblasts, RGS5+ and TAGLN+ pericytes populations largely colocalize, implying selective expansion of the RGS5+ pericytes during tumour angiogenesis." (PMID 38165934, 2024).
tumor (continued). "Genetic targeting of TAGLN reduced in vivo tumor growth in GBM, resulting in an increase in survival of tumor‐bearing mice, supporting TAGLN as an effective target." (PMID 38087889, 2024). "Our results showed that TAGLN was down-regulated in BLCA cells, supporting that TAGLN is an anti-tumor gene." (PMID 37274283, 2023). "Three genes, SERPINB2, TAGLN, and HIST1H2BD, showed high expression and significant differences between normal and tumor tissue in this analysis." (PMID 36982651, 2023). "TAGLN and HIST1H2BD were considerably stronger when expressed in tumor tissue compared to healthy tissue." (PMID 36982651, 2023). "The results revealed that SPP1, COMP, THBS2, SERPINE1, and COL11A1 were highly expressed in tumor tissues, while MYH11, TAGLN, and CNN1 were lowly expressed." (PMID 36999888, 2023). "The differential analysis also confirmed the high expression of CD74, HLA-DRA, C7, CCL12, and CCR3 in CAFs from P-LN but lower expression of VIM, APOD, MMP11, TAGLN, and CDKN2A compared with that in the primary tumor." (PMID 36569924, 2022). "After intersecting genes in the yellow module of WGCNA with DEGs, we identified five myCAFs marker genes defined by previous single-cell sequencing that were significantly down-regulated in tumor tissues, including ACTA2, MYL9, TAGLN, TPM1, and TPM2." (PMID 35309916, 2022). "In prostatic cancer (PC), TAGLN (tumor suppressor) and HLA had higher expression in the periphery, whereas NUPR1 and KLK4 etc. were expressed higher in the tumor core." (PMID 36313703, 2022). "The function of the key protein, transgelin, was studied using CRISPR/Cas9 and RNA interference (RNAi) in cell lines derived from ccRCC tumors to confirm its role in RCC tumor development and sunitinib resistance." (PMID 34572331, 2021). "We further detected the expression changes of Transgelin in normal esophageal tissues, LGIN, HGIN, and tumor by immunohistochemistry." (PMID 34552870, 2021). "The functional data based on CRISPR and RNAi clearly confirmed that transgelin is essential for the proliferation of RCC cells, and it is also an important parameter of tumor cell aggressiveness and their ability to form metastases." (PMID 34572331, 2021). "In current study, we investigated the role of TGFβ-mediated TAGLN expression in the proliferation, migration, and clonogenic potential of CRC cells in vitro and tumor formation in vivo." (PMID 32393769, 2020). "Our data describe a model for the molecular mechanisms linking TGFβ-induced upregulation of TAGLN and CRC tumor progression." (PMID 32393769, 2020). "Therefore, we believe that transgelin may serve as a biomarker for tumor metastasis." (PMID 32774160, 2020). "On immunohistochemical examination, the tumor cells express smooth muscle cell markers: HHF35, desmin, smooth muscle myosin heavy chain, h-caldesmon, and recently transgelin." (PMID 27633779, 2016). "Univariate analysis showed that the expression of R-Ras and Transgelin, CEA level, tumor differentiation and AJCC stage were significant prognostic factors for OS and DFS in patients undergoing “curative” surgery." (PMID 27270312, 2016). "We compared the transgelin protein levels between the PN and MPNST tumor tissues using IHC analysis." (PMID 25109740, 2014). "In particular, transgelin is a negative regulator of MMP-9 expression and a suspected tumor suppressor." (PMID 20152043, 2010). "This tissue staining revealed TAGLN protein along blood vessels as expected, but also within the tumor stroma without direct contact with vessel-like structures." (PMID 39516494, 2024). "To further explore the importance of transgelin in tumor progression in vivo, we mixed LLCs and TaglnOE iMEFs or Taglnsh1 iMEFs, at a ratio of 1:3 and inoculated them into C57BL/6 mice to establish a model of subcutaneous tumor transplantation." (PMID 36990991, 2023).
tumor (continued). "In order to investigate and compare the co-expression of adhesion molecules (CDC42, TAGLN, and GSN) in cancerous and healthy samples, 100 co-expressed genes were retrieved from GEPIA2 using data from TCGA COAD tumor samples, TCGA adjacent normal tissue samples, and GTEx healthy colon samples." (PMID 37365287, 2023). "Increased expression of ACTA2, FLNA, TAGLN, and TPM1 may promote the transformation of macrophages into M2 in the tumor microenvironment." (PMID 37274283, 2023). "On the other hand, expression of the myCAF markers Acta2 (α-SMA gene) and Transgelin (Tagln) in PSCs cocultured with tumor organoids was not affected by hypoxia." (PMID 36109493, 2022). "Transgelin in complex or in interaction with other proteins significantly contributes to EMT initiation and modulation by affecting cell migration and promotion in different tumor types." (PMID 34572331, 2021). "The cellular immunofluorescence experiments and SEM showed that COMP could interact with TAGLN to regulate cell remodeling and promote EMT in tumor cells." (PMID 32754278, 2020). "The most prominent epithelial cell population in each tumor expressed luminal cell and luminal progenitor markers, while in some tumors (e.g., tumor 89), a minority population was evident that expressed markers of myoepithelial cells including ACTA2 and TAGLN." (PMID 30181541, 2018). "Although transgelin levels affected the number and size of metastases, there were no consistent differences in tumor histology." (PMID 26847345, 2016). "We observed that low expression of R-Ras or Transgelin was correlated with the tumor tissues, but not with the para-tumor tissues." (PMID 27270312, 2016). "However, as the patient tumor datasets contain a wide variety of cell types including immune, endothelial, and fibroblast cells, these cells were first removed from our analysis based on the expression of PTPRC (CD45), ESM1, and TAGLN respectively." (PMID 40241258, 2025). "To begin to determine what might be the role of CCN1 expression by CAFs, we used CAF single-cell expression data to identify a group of six genes (PDGFRA, COL1A1, DCN, TAGLN, COL6A3, and LPAR1) that strongly correlated with CCN1 expression, yet were minimally expressed in other tumor cell types." (PMID 38363129, 2024). "To explore TAGLN and HDAC2 expression in GBM patient surgical specimens, we performed IHC staining and observed that HDAC2 (which is a hypoxia‐related gene), TAGLN, CA9 (a hypoxic marker), and HIF1α were all located in GBM tumor cell nuclei and highly expressed in pseudopalisades (upper)." (PMID 38087889, 2024). "However, there was no effective correlation between TAGLN and sex (P = 0.277), age (P = 0.183), tumor size (P = 0.629)." (PMID 35665757, 2022). "Additionally, TAGLN-depleted RKO cells exhibited reduced tumor formation in vivo, corroborating the in vitro results, thus highlighting an important role for TAGLN in driving CRC migration and tumor formation." (PMID 32393769, 2020). "At least part of the discrepancies in the expression levels of TAGLN in different studies has been explained as a result of higher TAGLN expression in the tumor stroma of invasive tumors rather than the tumor tissue itself, which is revealed by subsequent IHC staining analyses." (PMID 26421063, 2015). "Next, to determine the functional role of transgelin in MPNST pathogenesis, we manipulated the TAGLN gene expression and investigated the alteration of the RAS-mitogen-activated protein kinase (MAPK) signaling pathway in the normal-phenotypic and malignant tumor cells." (PMID 25109740, 2014). "To examine the functional role of transgelin in MPNST pathogenesis, we manipulated the TAGLN gene expression and investigated if the RAS signaling was altered according to the transgelin expression level in the normal-phenotypic cells and malignant tumor cells." (PMID 25109740, 2014).